INSM1 (INSM transcriptional repressor 1)
Diseases named in the same sentence as INSM1 in open-access papers (continued):
Sharing a sentence is not in itself a finding about the gene and the disease.
insulinoma (20 papers, 2015 to 2025). "Insulinoma-associated protein 1 (INSM1), a transcription factor from the insulinoma-associated protein family, plays a pivotal role in cell proliferation, differentiation, migration, and neurodevelopment." (PMID 41220942, 2025). "Neuroendocrine differentiation markers, such as insulinoma‐associated protein‐1 (INSM1), encoded by the insulinoma‐associated protein‐1 gene, can promote breast cancer development by regulating C‐MYC." (PMID 40550558, 2025). "An insulinoma associated-1 (INSM1) gene is a transiently expressed zinc-finger transcription repressor in developing NE cells that was originally identified in a human insulinoma subtraction library." (PMID 37627018, 2023). "Insulinoma-associated-1 (INSM1) is a zinc-finger transcription factor that was originally identified in a human insulinoma subtraction library." (PMID 36290282, 2022). "An insulinoma-associated-1 (INSM1) zinc-finger transcription factor has emerged as an NB biomarker that plays a critical role in facilitating tumor cell growth and transformation." (PMID 36290282, 2022). "A novel marker called insulinoma-associated protein 1 (INSM1) has been identified in insulinoma tissue and subsequently detected in different NE human cells and tumors." (PMID 34008122, 2021). "Among them, INSM1 (Insulinoma-associated protein 1) is a zinc-finger transcriptional factor originally isolated from pancreatic insulinomas." (PMID 31330946, 2019). "This locus was tightly linked to the gene encoding Insm1, a beta cell transcription factor that was highly expressed in human insulinomas but unexpressed in other types of PanNETs due to promoter hypermethylation." (PMID 30796198, 2019). "Insulinoma-associated protein 1 (Insm1 or IA-1) is a conserved zinc-finger transcription factor that was originally cloned from a human insulinoma subtraction library." (PMID 28824372, 2017). "Insulinoma associated-1 (IA-1/INSM1) was originally cloned from a human insulinoma subtraction library." (PMID 27072116, 2016). "The IA-1 gene was later renamed in the GenBank database as INSM1 (insulinoma-associated-1)." (PMID 34943408, 2021). "Next we tested whether allelic differences in the Insm1 genes encoded by the B6 and A/J lineages might be responsible for the insulinomas and NF-PNETs observed in RT2 B6 and RT2 AB6F1 mice, respectively." (PMID 30796198, 2019). "Insulinoma associated-1 (IA-1/INSM1) was originally cloned from an insulinoma subtraction library." (PMID 26456864, 2015). "ASCL-1 also regulates the expression of NE markers such as NCAM1, insulinoma-synaptophysin (SYP), insulinoma associated protein 1 (INSM1), chromogranin A (CHGA), and CGRP." (PMID 39858036, 2025). "INSM1, a zinc-finger transcription factor originally discovered in an insulinoma subtraction library, is highly expressed in embryonic NE precursors and NE tumors." (PMID 41514864, 2025). "For instance, the exclusive activity of the INSM1 promoter in insulinoma tumors has been leveraged for adenoviral therapy in insulinoma treatment." (PMID 38213995, 2024). "INSM1 is a transcription factor isolated from an insulinoma subtraction library." (PMID 37627018, 2023). "Second, Insm1 expression was lower in NF-PanNETs, compared to insulinomas." (PMID 30796198, 2019). "The diagnosis of LCNEC requires positive immunohistochemical staining with chromogranin A, synaptophysin, and CD56, along with a morphological diagnosis, and insulinoma-associated protein 1 (INSM1) has been proposed as an additional marker but is still not an ideal or better marker." (PMID 38067335, 2023). "Expression of Insm1 mRNA was higher in the insulinomas from RT2 B6 and lower in nonfunctioning tumors from RT2 AB6F1 mice." (PMID 30796198, 2019). "In a hybrid AB6F1 genetic background, low expression levels of a beta cell transcription factor, Insm1, favors development of nonfunctioning tumors, whereas in a C57Bl/6 genetic background, higher expression of Insm1 favors development of insulinomas." (PMID 30796198, 2019).
insulinoma (continued). "These experiments suggested that Insm1 might be relevant to the insulinomas and to the nonfunctioning tumors observed in RT2 mice." (PMID 30796198, 2019). "These different lines of evidence suggest that Insm1 plays an important role as a tumour-suppressor gene for NfpNETs and that differences in its level of expression can direct β-cell transformation toward either a differentiated insulinoma or a metastatic and more aggressive nonfunctioning form." (PMID 33126717, 2020). "Interestingly, low expression of Insm1 in RT-2 AB6F1 mice leads to the formation of larger, more invasive and metastatic nonfunctioning tumours, compared to the more differentiated insulinomas in RT-2 B6 models, that express higher levels of Insm1." (PMID 33126717, 2020).
neuroendocrine carcinoma (17 papers, 2019 to 2026). A malignant neuroendocrine neoplasm composed of cells containing secretory granules that stain positive for NSE and chromogranin. "In particular, insulinoma-associated protein 1 (INSM1) is a specific biomarker for neuroendocrine cancers, but its expression is also detected in liposarcomas." (PMID 38254762, 2024). "For neuroendocrine carcinoma specifically, a recent study investigated the status of insulinoma-associated protein 1 (INSM1) in a variety of head and neck neuroendocrine carcinomas." (PMID 32725435, 2020). "However, in other tumor models—such as pulmonary high-grade neuroendocrine carcinoma-positive INSM1 protein expression has been associated with a dismal prognosis, in line with the data on INSM1 gene expression levels from the present study." (PMID 36121500, 2022). "Our data confirm that INSM1 gene is highly expressed in neuroendocrine carcinomas of different sites." (PMID 35608806, 2022). "For high grade neuroendocrine carcinomas of the uterine cervix, INSM1 was more sensitive (92% of cases) than SYP and CgA (both reactive up to 86% of cases), and its expression was also more clearly interpretable due to its nuclear staining." (PMID 34943408, 2021). "The second-generation neuroendocrine markers insulinoma-associated protein 1 (INSM1), ISL1, and secretagogin, have high sensitivity and specificity for neuroendocrine differentiation, expressed even in poorly differentiated neuroendocrine carcinomas." (PMID 35008368, 2021). "Another study reported INSM1 expression in two cases of HPV-related neuroendocrine carcinoma in cytology series from two different institutions." (PMID 34943408, 2021). "Location seems to determine the effectiveness of INSM1 staining for neuroendocrine carcinomas (NEC) in the female genital tract." (PMID 34943408, 2021). "HPV-related neuroendocrine carcinomas have been described with small cell, large cell, or combined cell populations, and INSM1 was expressed along with other NE markers." (PMID 34943408, 2021). "Neuroendocrine carcinoma are high-grade malignant neoplasms with cells that express little or no chromogranin A, somatostatin receptors, or hormones; however, high expression of INSM1 and synaptophysin has been observed in neuroendocrine carcinoma." (PMID 40491286, 2026). "In the head and neck area, sinonasal neuroendocrine carcinoma, neuroendocrine carcinomas localized in the hypopharynx, larynx, trachea and parapharyngeal space, as well as HPV-related neuroendocrine carcinomas, paraganglioma, and medullary thyroid carcinoma were shown to be immunoreactive for INSM1." (PMID 34943408, 2021). "The aberrant expression of INSM1 could be found in various cancers, such as head and neck tumors (Rooper, Bishop, & Westra, 2018), neuroendocrine carcinoma, Merkel cell carcinoma (Lilo, Chen, & LeBlanc, 2018), and small cell lung cancer." (PMID 31131446, 2019). "Focal or aberrant staining for synaptophysin, chromogranin A, CD56 or INSM1 may occur in otherwise conventional gynecologic carcinomas, whereas true poorly differentiated neuroendocrine carcinomas represent aggressive tumors with distinct prognostic and therapeutic implications." (PMID 42196939, 2026). "The second-generation neuroendocrine markers insulinoma-associated protein 1 (INSM1), ISL1, and secretagogin show high sensitivity and specificity for neuroendocrine differentiation and maintain the expression even in poorly differentiated neuroendocrine carcinomas." (PMID 37324272, 2023). "CpGs of lower methylation in VP-MCC cell lines were associated with neuroendocrine marker genes such as SOX2 and INSM1, or linked to binding sites of EZH2 and SUZ12 of the polycomb repressive complex 2, i.e., genes with an impact on carcinogenesis and differentiation of neuroendocrine cancers." (PMID 34667274, 2022). "INSM1 is a highly sensitive marker for MCC, although specificity is limited relative to other neuroendocrine carcinomas." (PMID 39136002, 2024).
neuroendocrine carcinoma (continued). "Notably, neuroendocrine cancer-related markers were significantly upregulated after SCLC transformation, such as SYP, CHGA, INSM1, etc.." (PMID 40437627, 2025). "In the head and neck area, sinonasal neuroendocrine carcinoma, neuroendocrine carcinomas localized in the hypopharynx larynx trachea and parapharyngeal space as well as HPV-related neuroendocrine carcinomas, paraganglioma and medullary thyroid carcinoma, are shown to be immunoreactive for INSM1." (PMID 34943408, 2021).
small cell lung carcinoma (10 papers, 2016 to 2025). Small cell lung cancer (SCLC) is a highly aggressive malignant neoplasm, accounting for 10-15% of lung cancer cases, characterized byrapid growth, and early metastasis. "Pulmonary NETs, including small cell lung carcinoma, large cell NE carcinoma, atypical carcinoid tumor and typical carcinoid tumor, expressed INSM1 with high specificity (97%) that was similar to CGA (98%) but greater than CD56 (87%) and SYP (90%)." (PMID 34943408, 2021). "INSM1 is highly expressed in medullary thyroid carcinoma, small cell lung cancer, and cervical carcinoma, and can regulate the biological behaviors of tumor cells." (PMID 32670859, 2020). "In this study, we used immunohistochemical staining to examine 35 cases of different clinical stages of small cell lung cancer and 5 normal lung tissues for INSM1 expression." (PMID 27072116, 2016). "INSM1 mRNA was detected by Northern blot analysis in 97 % (30 of 31) of small cell lung cancer cells and 13 % (4 of 30) of non-small cell lung cancer cells with NE phenotype." (PMID 27072116, 2016). "Similarly, INSM1 is highly expressed in small cell lung cancer tissues and cells, and INSM1 knockdown inhibits the malignant biological behaviors of small cell lung cancer cells." (PMID 32670859, 2020). "All the small cell lung cancer tissues were strongly positive for INSM1." (PMID 27072116, 2016). "We found that SOX11 showed a sensitivity similar to INSM1 and CGA, and less than SYN and CD56 in small cell lung carcinomas (SCLCs) and large cell neuroendocrine carcinomas (LCNECs)." (PMID 34996493, 2022). "(b) Heat map of the PEA3 family ETS transcription factors (ETV1, ETV4, and ETV5) and neuroendocrine transcription factors (ASCL1, NEUROD1, INSM1, and POU3F2 [BRN2]) in small cell lung cancer and lung adenocarcinoma cell lines." (PMID 34121659, 2021). "The expression pattern of INSM1 in NE lung cancer is consistent with the previous Northern blot analysis that revealed INSM1 mRNA is highly expressed in nearly 100 % of small cell lung carcinomas (SCLC) cell lines but not in normal adult lung tissues." (PMID 27072116, 2016).
breast carcinoma (9 papers, 2020 to 2025). "INSM1 expression has also been associated with improved disease-free survival in luminal breast cancers, supporting its inclusion alongside synaptophysin ± chromogranin in diagnostic panels." (PMID 40909459, 2025). "We assessed the applicability of two novel markers, syntaxin-1 and insulinoma-associated protein 1 (INSM1) in breast carcinomas." (PMID 34764822, 2021). "Depletion of SCAMP1-TV2 reduced its interaction with PUM2 and enhanced the PUM2 and INSM1 interactions, leading to INSM1 mRNA degradation in breast cancer." (PMID 35992869, 2022). "The inhibitory effects of PUM2 overexpression on the malignant biological behaviors of breast cancer cells was reversed by INSM1 overexpression." (PMID 32670859, 2020). "Silencing INSM1 significantly inhibited the proliferation, migration, and invasion of the breast cancer cells while promoting the apoptosis, which indicates that INSM1 acts as a carcinogenic factor in breast cancer." (PMID 32670859, 2020). "In this study, the endogenous expression of SCAMP1-TV2, PUM2, and INSM1 in breast cancer tissues and cells was determined." (PMID 32670859, 2020). "Assessment of the mRNA expression in breast cancer cells after PUM2 overexpression showed that the expression of INSM1 was downregulated more significantly by PUM2 overexpression." (PMID 32670859, 2020). "In addition, it has been shown that INSM1, by regulating the activity of C-MYC and p-ERK pathways, can promote breast cancer development, and a large clinical trial recommends INSM1 in cases of IBC with neuroendocrine differentiation." (PMID 40565772, 2025). "Breast cancer occasionally is focally and weakly positive for INSM-1." (PMID 34943408, 2021). "At present, the expression and potential regulatory effects of INSM1 in breast cancer currently remains unclear." (PMID 32670859, 2020). "The emergence of INSM1 as a more sensitive “second-generation” biomarker for neuroendocrine differentiation in the breast holds promising prospects for improved diagnosis of breast NETs, which are difficult to distinguish from other types of breast carcinomas based on histologic features alone." (PMID 34943408, 2021). "Therefore, we further detected the role of INSM1 in breast cancer." (PMID 32670859, 2020). "As compared to the PUM2-NC+ INSM1-NC group, the viability, migration, and invasion of breast cancer cells were decreased in the PUM2+INSM1-NC group, but the apoptosis rate was increased; the contrary results were found in PUM2–NC+INSM1 group." (PMID 32670859, 2020). "Silencing SCAMP1-TV2 inhibits the malignant biological behaviors of breast cancer cells by reducing its binding to PUM2 and further increasing the binding of PUM2 to INSM1 mRNA." (PMID 32670859, 2020). "Recently, a tissue microarray analysis showed that adding chromogranin to synaptophysin detects an extra 4.2% of breast cancer cases with neuroendocrine differentiation, while INSM1 identifies 15% of cases negative for both." (PMID 40909459, 2025).
lung carcinoma (9 papers, 2016 to 2025). "Background and Objective: Insulinoma-associated protein 1 (INSM1) is a novel immunohistochemical marker with potential utility in identifying neuroendocrine differentiation in lung cancer." (PMID 40805240, 2025). "Furthermore, a large study discovered insulinoma-associated protein 1 (INSM1) was more sensitive (100% positive) than chromogranin (85%) in SCNE lung carcinoma." (PMID 37467967, 2023). "This study presents the first meta-analysis assessing the diagnostic accuracy of using INSM1 to distinguish LCNEC and SCLC from other lung cancer subtypes, addressing the variability across individual studies." (PMID 40805240, 2025). "This was also supported by ASCL1 (Mash1 human homolog), which regulates INSM1 gene through E2-box binding in NE lung cancer cells." (PMID 37627018, 2023). "Next we examined the expression of SOX11 in normal lung tissue and different types of lung cancers, which is compared with the expression of INSM1, SYN, CGA and CD56." (PMID 34996493, 2022). "In most of the lung cancer cells examined, INSM1 expression showed high concordance with the other specific NE markers, synatophysin, L-dopa decarboxylase, and chromogranin A." (PMID 27072116, 2016). "We initiated our study to dissect the functional effect of INSM1 transcription factor in normal lung development since INSM1 is a sensitive and specific NE lung cancer marker." (PMID 27072116, 2016). "Our findings suggest that INSM1 could be used as a reliable single marker in lung cancer diagnosis, which may simplify testing and improve consistency in pathology laboratories." (PMID 40805240, 2025). "A normal functional role of INSM1 is critical for the development of chromaffin cells, pituitary endocrine cells, pancreatic islets, lung cancer cells of NE origin, early differentiation of sympathetic neurons, sensory neurons of the dorsal root ganglion, and olfactory neurons." (PMID 37627018, 2023). "SHH was described to target INSM1 and promote the progress of lung cancer." (PMID 33282942, 2020). "The regulatory potential of NE-DMRs was further validated in vitro using paired ATAC- and RNA-seq and revealed both proximal and distal regulatory elements of canonical NE-marker genes such as CHGA, NCAM1, INSM1, as well as a number of novel candidate markers of NE lung cancer." (PMID 32707835, 2020). "Furthermore, INSM1′s nuclear staining pattern offers a distinct interpretive advantage over traditional cytoplasmic markers, particularly in small biopsy or cytology specimens, which are often the only available samples for diagnosis in advanced-stage lung cancer." (PMID 40805240, 2025).
neuroblastoma (6 papers, 2015 to 2025). Neuroblastoma (NB) is the most common solid, extracranial childhood tumor. "More recently, other regulatory genes were investigated, including INSM1 that is activated by MYCN gene, expressed in a large fraction of neuroblastomas and associated to a shorter survival." (PMID 36121500, 2022). "INSM1 transcription factor has emerged in vitro as a neuroblastoma biomarker that plays critical role in facilitating tumor cell growth and transformation." (PMID 36121500, 2022). "Here, we identified INSM1 as a novel target gene activated by N-myc in N-myc amplified neuroblastoma cells." (PMID 26456864, 2015). "The invasion assay and the xenograft nude mouse tumor model revealed that the INSM1 factor facilitated growth and oncogenesis of neuroblastoma." (PMID 26456864, 2015). "Using over-expression and knockdown experiments in neuroblastoma cells, we showed that INSM1 is critical for cell proliferation, BME-coated invasion, and soft agar colony formation." (PMID 26456864, 2015). "The current data supports our hypothesis that a positive-feedback loop of sonic hedgehog signaling induced INSM1 through N-myc and INSM1 enhanced N-myc stability contributing to the transformation of human neuroblastoma." (PMID 26456864, 2015). "In conclusion, we identify a strong prognostic impact of neuroendocrine-lineage transcriptional profiles in neuroblastoma, and suggest that the evaluation of NOTCH1, INSM1, YAP1, and NEUROD1 might help to further characterize the risk of relapse in neuroblastoma patients." (PMID 36121500, 2022).